FGFR1 (fibroblast growth factor receptor 1)
Diseases named in the same sentence as FGFR1 in open-access papers (continued):
Sharing a sentence is not in itself a finding about the gene and the disease.
cancer (continued). "Therefore, FGFR1 amplification may be an oncogenic driver mutation in tobacco-associated cancers of the aerodigestive tract." (PMID 25537505, 2015). "Our pan-cancer analysis of the COSMIC database of somatic mutations in cancer found a total of 1,749 mutations distributed across the entire kinase domains of FGFR1–4." (PMID 41361008, 2026). "The carcinoma population had a very high TFx (0.96), with 34 sCNA and regions containing FGFR1, CCND1, GNAS, and BRAF the most amplified." (PMID 41144934, 2026). "Overexpression of FGFR1 has been observed in cancers such as breast, lung, ovarian, bladder, prostate, and gastric cancers, among others." (PMID 40934169, 2025). "The FGFR1 gene is frequently amplified in diverse cancers including lung, head and neck and urothelial cancer." (PMID 40806483, 2025). "Fibroblast growth factor receptor 1 (FGFR1) is crucial in the progression of various cancers, participating in the processes of cell proliferation, survival, and differentiation." (PMID 41424604, 2025). "FGFR1 is a receptor that is expressed throughout the human body and shows aberrations in all kinds of cancers." (PMID 40806483, 2025). "Over‐activation or amplification of FGFR1 has been found to occur in many different cancers including oral squamous cell carcinoma, breast cancer, and lung cancer." (PMID 34038603, 2025). "The dynamic interplay between NRG1–HER3 and FGFR1 signaling reveals the molecular basis of cancer cell plasticity and clinically relevant strategies to target it." (PMID 39753722, 2025). "Combining an FGFR1 blockade with other anti-cancer drugs can be an interesting strategy for cancers that exhibit abnormal FGFR1 expression." (PMID 40149537, 2025). "Our assay also reported FGFR1/2/3 fusions in 0.68% of samples, though prevalence was higher in biliary (8.21%) and urothelial (3.01%) cancer samples." (PMID 40711866, 2025). "Together, these data suggest that adding FGFR1-targeting agents to the current alpelisib-fulvestrant regimen enhances cancer inhibition." (PMID 40510030, 2025). "Among the various molecular players in cancer progression, fibroblast growth factor receptor 1 (FGFR1) has emerged as a critical target for therapeutic intervention." (PMID 40547805, 2025). "FGFR1 amplification or overexpression has been identified in a variety of cancers, where it drives oncogenic processes." (PMID 40547805, 2025). "Together, these results demonstrate that the plastic engagement of either FGFR1 or HER3 allows cancer cells to adapt to different environmental cues." (PMID 39753722, 2025). "In this study, we designed a self-assembling RNA nanoparticle targeting three oncogenes-hTERT, BIRC5, and FGFR1-key drivers of cancer progression." (PMID 41594586, 2025). "In terms of CNAs, the cancer maintained the FGFR1 amplification and PIK3R1 deep deletion from the primary sample and acquired an amplification in AURKA in the metastatic sample." (PMID 40379787, 2025). "Fibroblast growth factor receptor 1 (FGFR1) plays a critical role in the progression of various cancers through its involvement in cell proliferation, survival, and differentiation." (PMID 40547805, 2025). "This perspective will explore the biological significance of FGFR1 in cancer progression, the mechanisms by which it contributes to immunotherapy resistance, and the emerging evidence supporting FGFR1-targeting therapies in combination with ICIs." (PMID 40547805, 2025). "Given the significant connection between FGFR1 overexpression and alpelisib resistance, we evaluated the effects of combining alpelisib with AZD4547, a selective FGFR1 inhibitor, on cancer cell inhibition." (PMID 40510030, 2025).
cancer (continued). "Dysregulation of the FGF/FGFR pathway is commonly observed in various cancers, and most studies have focused on FGFR1, FGFR2, and FGFR3 modulation." (PMID 41049266, 2025). "This article explores the role of FGFR1 in cancer biology, its contribution to immunotherapy resistance, and the therapeutic potential of targeting FGFR1 to enhance the efficacy of ICIs." (PMID 40547805, 2025). "With prolonged exposure, however, cells acquired resistance, characterized by the sustained activation of ERK, AKT, and STAT1, allowing cancer cells to bypass FGFR1 inhibition." (PMID 41315241, 2025). "Collectively, these findings underscore the significant role of FGFR1 overexpression in therapeutic resistance, highlighting the importance of targeting FGFR1 signaling to improve treatment outcomes across various cancers." (PMID 40510030, 2025). "Consistent results were obtained in cells with FGFR1 knockdown, indicating that simultaneous inhibition of FGFR1/STAT3 signaling greatly promotes the anti-cancer activity of Erdafitinib." (PMID 39247610, 2024). "In these cancer types, the expression of eight different miRNAs was negatively correlated with FGFR1 mRNA levels." (PMID 40135140, 2024). "FGFR1 has been previously shown to be essential for GnRH neurons, which promote cell proliferation and inhibit apoptosis in cancer cells." (PMID 38654040, 2024). "By targeting FGFR1 kinase, honokiol appears to be a promising compound for enhancing the efficacy of anti-cancer drugs." (PMID 39329123, 2024). "In vitro experiments have shown that IMB-R1 significantly inhibits the growth of cancer cells’ overexpression of FGFR1 and induces apoptosis." (PMID 39590377, 2024). "ABM, Agent-based model; CAF, cancer-associated fibroblast; ECM, extracellular matrix; FGFR1, fibroblast growth factor receptor-1; FN, fibronectin; MDE, matrix-degrading enzymes; MMP, matrix metalloproteinases." (PMID 39449986, 2024). "Fibroblast growth factor (FGF) ligands and receptors (FGFR1-4) play a crucial role in cancer development by activating mitosis and mesodermal signaling pathways." (PMID 39697545, 2024). "FGF2 promoted the growth of CAFs through FGFR1 signalling, resulting in cancer cell proliferation, migration, invasion and angiogenesis." (PMID 40135140, 2024). "This overexpression can enhance the FGFR1 signaling pathway, promoting cell proliferation, survival, and migration, which are key processes in cancer development and progression." (PMID 39590377, 2024). "VEGF-B exhibited different effects on angiogenesis dependent on the extent of its binding to FGF/FGFR1 in cancer." (PMID 38195474, 2024). "FGFR1 activity is coordinated at multiple steps and unbalanced FGFR1 signaling contributes to developmental diseases and cancers." (PMID 38750548, 2024). "The fibroblast growth factor receptor (FGFR) family consists of four transmembrane receptor proteins (FGFR1-4), and genomic alterations of these receptors have been documented in various types of cancers." (PMID 39031286, 2024). "To show that p21 is a crucial regulator mediating the effects of FGF2 on cell proliferation in FGFR1 amplified cancer cells, we used propidium iodide (PI)-based cell cycle analysis with flow cytometry." (PMID 38553760, 2024). "Recent research has highlighted the role of FGFR1 signaling as a pivotal regulator of inflammation, implicating its involvement in numerous chronic inflammation-related disorders, such as cancer." (PMID 39377013, 2024). "To systematically evaluate the activation of FGFR1 signaling, we performed single-sample gene set enrichment analysis (ssGSEA) to identify the levels of FGFR1 activation for 499 cancer samples using 3 different FGFR1-related REACTOME gene sets." (PMID 38781024, 2024). "We revealed that both honokiol and FGF ligand trap prevent FGF1-dependent protection against taltobulin in cancer cells expressing FGFR1." (PMID 39329123, 2024).
cancer (continued). "For example, the amplification of FGF receptor 2 (FGFR2), which is less frequent than the amplification of FGF receptor 1 (FGFR1) across cancer types, is often reported in patients with gastric-esophageal junction adenocarcinoma." (PMID 39691707, 2024). "Our results indicated that high FGFR1 groups had elevated p21/CCND1 ratios, reduced M and S phases, and heightened cancer stemness traits, while low FGFR1 groups demonstrated less impact or a contrary trend." (PMID 38553760, 2024). "Gene fusions of FGFR family members (FGFR1–3) with various other partner genes are identified in several cancers, including breast, carcinomas, and adenocarcinomas." (PMID 37509254, 2023). "Interrogating PSC-cancer cell interactions in 3D models, we identified nuclear FGFR1 as critical for PSC-led invasion of cancer cells." (PMID 36357571, 2023). "In GBM, FGFR1 is known to regulate cancer stemness and therapy resistance through the transcription factor ZEB1, which is also regulating GBM invasion." (PMID 37579831, 2023). "FGFR-targeted therapies have emerged as a promising approach to inhibit FGFR1 signaling and selectively target cancer cells with FGFR1 overexpression." (PMID 37373291, 2023). "Besides the numerous FGFR alterations in adult cancers, some alterations are strongly associated with pediatric low grade neuroepithelial lesions such as FGFR1 duplication, and FGFR1/3-TACC1 or FGFR2-CTNNA3 fusions may be considered as hallmarks of these tumors." (PMID 36495366, 2023). "SK-RC-31 is a von Hippel-Lindau (VHL) mutant cancer cell line that excessively accumulates FGFR1 on PM as a result of defective endocytic internalization of surface FGFR1." (PMID 38136383, 2023). "In conclusion, the FGF3/FGFR1/STAT3 signaling pathway is one of the mechanisms by which FGF3 promotes cancer." (PMID 37496658, 2023). "NAB2–STAT6 fusions have been shown to function as transcriptional activators and upregulate the expression of cancer-promoting EGR1 target genes including FGFR1 and NTRK1, as well as IGF genes in SFT patient samples." (PMID 37370737, 2023). "Our results show that the developed conjugate efficiently targets FGFR1-positive cancer cells, leading to excellent and selective toxicity." (PMID 37373291, 2023). "Balanced FGF/FGFR1 signaling is crucial for the development and homeostasis of the human body, and aberrant FGFR1 is frequently observed in various cancers." (PMID 37480072, 2023). "Enhanced FGFR1 signaling stimulates cell proliferation, increases cell plasticity and invasiveness, and makes cancer cells resistant to chemotherapy 3-5." (PMID 36778115, 2023). "Our results confirm that the FGF2 dimer with a specific well-defined topology can serve as an effective drug delivery vehicle for targeting cancer cells that overproduce FGFR1." (PMID 37373291, 2023). "Qualitative alterations in FGFR1-3, such as mutations and rearrangements, are sensitive to FGFR inhibitors in various cancer types, whereas quantitative alterations, such as amplification, seem to be less effective targets." (PMID 37493315, 2023). "We screened an anti-cancer compound library and identified fibroblast growth factor receptor 1 (FGFR1) promoting alectinib-induced anaplastic lymphoma kinase (ALK) fusion-positive DTP cell’s survival." (PMID 37880373, 2023). "In order to identify additional genomic mechanisms driving FGFR1-dependent cancers, we therefore plotted and analyzed the average copy number for these 2 groups." (PMID 37606995, 2023). "Others and we have demonstrated that FGFR1 is expressed on GSCs, with FGF2 binding to FGFR1 activating downstream signaling pathways that maintain cancer stemness." (PMID 37579831, 2023).
cancer (continued). "Previously, we demonstrated the efficacy of fibroblast growth factor 1 (FGF1) and 2 (FGF2) as a targeting molecules for FGFR1-overproducing cancer cells." (PMID 37373291, 2023). "Clinical trials evaluating FGFR1-targeted monoclonal antibodies, such as bemarituzumab and futibatinib, are underway in various cancer types." (PMID 37373291, 2023). "The aim of this study was to characterize FGFR1 as NB cancer-driver gene and to evaluate its role as therapeutic target with in vitro studies." (PMID 35488346, 2022). "Exposure of TGF-β in epithelial cells and cancer cells increased the expression of FGFR1 and decreased the expression of FGFR2." (PMID 36140527, 2022). "Previous whole-genome CRISPR screening demonstrated the fibroblast growth factor receptor 1 (FGFR1) as the top-ranked target that promoting the survival of mesenchymal phenotype-related cancer cells." (PMID 35836817, 2022). "Cohort 4 of this study assesses the utility of combination therapy with fulvestrant in FGFR1-amplified hormone receptor-positive cancer, with results anticipated to be available in 2023/2024." (PMID 35193394, 2022). "Recently, FGFR inhibitors have been highlighted as promising targeted drugs due to the high prevalence of FGFR1 amplification in cancer patients." (PMID 36139037, 2022). "In the present study, TMT-labeled mass spectrometry-based proteomics suggested that FGFR inhibition regulated glucose metabolism in a FGFRi-sensitive cancer cell line NCI-H1581 with FGFR1 amplification." (PMID 36168616, 2022). "Mesenchymal EGFR mutant cancers survived initial EGFR inhibitors because fibroblast growth factor receptor 1 (FGFR1) was expressed on the cell surface." (PMID 36313710, 2022). "FGFR mutations are frequent in human cancers, with the highest prevalence in NSCLC (FGFR1 range 0–18%), endometrial carcinoma (FGFR2, range 0–9%), bladder carcinoma (FGFR3, range 8.5–26%), and rhabdomyosarcoma (FGFR4 7.5%)." (PMID 35402233, 2022). "In this study, we addressed this issue by using radioresistant human cancer cell lines H1703 (FGFR1 mutant), A549 (FGFR1–4 wild-type), and H1299 (FGFR1–4 wild-type)." (PMID 35681425, 2022). "Human cancer cell lines showed co-amplification of FGFR1-4EBP1 (6–9%), and this was mutually exclusive with PI3K mutations observed in 20% of the samples in Cell Line Encyclopedia." (PMID 35626002, 2022). "FGF signaling also protects from LDHA degradation and deletion of FGFR1 blocks to use lactate as a main energy source and LDHB expression is associated with poor survival in cancer patients." (PMID 36077431, 2022). "FGFR1-mediated metabolic LDHA activation and LDHB deactivation are associated with cancer growth and progression." (PMID 36077431, 2022). "H1581 is characterized by high focal amplification of FGFR1 overexpression, which is related to increased aggressiveness, metastasis, and poor prognosis in various cancer types (especially in NSCLC)." (PMID 35955773, 2022). "Mechanistically, for the first time, we revealed that FGFR inhibition suppressed HK2 gene transcription via inhibiting mTOR in FGFRi-sensitive in vitro and in vivo cancer models with different FGFR1-4 anomalies." (PMID 36168616, 2022). "FGFR1 regulates cell–cell adhesion and extracellular matrix architecture and acts as oncogene in several cancers." (PMID 35488346, 2022). "FGFR amplification (mainly in FGFR1 and 2) causes overexpression of proteins and increases the FGFR-dependency of cancer cells." (PMID 35494629, 2022). "FGFR1 activation contributes to aerobic glycolysis and transformation of epithelial cells or reprograming the energy metabolism of cancer cells." (PMID 36185201, 2022). "Highly expressed FGFR1 has the potential to promote nuclear factor-kappaB (NF-kappaB) signaling in cancer." (PMID 35081975, 2022). "The radiosensitizing effects of LY2874455 on FGFR1–4 wild-type cancer cells imply a role for canonical FGF signaling in irradiated cells via the activation of downstream cytoprotective pathways." (PMID 35681425, 2022).
cancer (continued). "The expression of FGFR1, which promotes the ability of cancer cells through the Ras-ERK pathway, was also confirmed." (PMID 36142409, 2022). "4EBP1 is phosphorylated by FGFR1 and PI3K signaling, and accordingly cancer with 4EBP1-FGFR1 amplification is more sensitive to FGFR1 and PI3K inhibition due to inhibition of 4EBP1 phosphorylation." (PMID 35626002, 2022). "Patients with EGFR mutant aNSCLC progressing on EGFR TKIs and developing an FGFR1/2/3 fusion were selected from the ED of Davidoff Cancer Center (DCC) and Oncology Department, Bnei-Zion hospital (BZ) (April 2014–April 2021)." (PMID 35566609, 2022). "Here, we evaluated the significance of N-glycosylation for the internalization and toxicity of conjugates targeting two model receptor tyrosine kinases strongly implicated in cancer: HER2 and FGFR1." (PMID 35955648, 2022). "Analysis of 4873 cancers found 61% of FGFR1-4 aberrations (7.1% of all cancers) were amplifications." (PMID 34068954, 2021). "The combination of palbociclib with FGFR-targeting AZD4547 resulted in remarkable synergistic effects on MCF-7/FGFR1 cells, especially for the inhibition of cancer cell stemness." (PMID 34831231, 2021). "Based on these findings we aimed to develop a modular, self-assembly system for generation of oligomeric cytotoxic conjugates, capable of FGFR1 clustering, for targeting FGFR1-overproducing cancer cells." (PMID 34635096, 2021). "In summary, we report GZD824 as a pan‐FGFR inhibitor which inhibits the signaling pathways of FGFR1 kinases and suppresses the proliferation of cancer cells harboring overexpression or mutant activation of FGFR1 in vitro and in vivo." (PMID 34114373, 2021). "Fgf-2 and its receptor Fgfr1 play a crucial role in both stromal and cancer cells in enhancing cancer cell survival." (PMID 34722255, 2021). "In contrast to FGFR1 amplification and FGFR3 mutation, research has shown that the response to AZD4547 among FGFR2-amplified cancers is strong." (PMID 34639155, 2021). "The relative comparison of IC50s between different cancer cell lines treated with FGFR1 inhibitor (AZD4547, FGFR3861, Foretinib, PD173074, Ponatinib) with a significant difference in primary and metastatic cell lines are shown." (PMID 33299129, 2021). "To determine the cytotoxic potency andFGFR1 selectivity of the3xGFPp_FGF1E_LPET_MMAE conjugate, we used a panel of cancer cell lineswith different levels of FGFR1 expression." (PMID 34855396, 2021). "To identify therapeutic opportunity in different cancer types, we interrogated the FGFR1 drug screen in various cancer cell lines." (PMID 33299129, 2021). "Our group has recently demonstrated beneficial effect of dual-warhead conjugates against FGFR1-positive cancer cells." (PMID 34635096, 2021). "In this regard, the amplification of FGFR1 in cancer cells was shown to trigger the recruitment and activation of STAT3." (PMID 33535617, 2021). "The T-Fc-vcMMAE conjugate presented in this manuscript efficiently kills cancer cells bearing FGFR1 protein on their surface, while it is neutral to the cells that lack this receptor." (PMID 33962559, 2021). "This was in part due to increased Aurora A and PLK1 activity, that are also found upregulated in the FGFR1-driven cancers." (PMID 34207779, 2021). "Estrogen deprivation led to an interaction between FGFR1 and ERα in the nucleus of cancer cells and subsequent regulation of ER-dependent genes transcription." (PMID 34830951, 2021). "The expression level of FGF1 and FGFR1 in these cancers indicated that FGF1 induce the invasion and metastasis of tumor cells." (PMID 34552869, 2021). "The aim of this study was to obtain highly internalizing cytotoxic conjugate of the T-Fc for specific delivery of drugs into FGFR1-positive cancer cells." (PMID 33962559, 2021). "Summarizing, our data confirm the applicability of the FGF1-SA oligomers as highly effective drug delivery vehicles for the selective treatment of FGFR1-producing cancer cells." (PMID 34635096, 2021).